DKK1 (dickkopf Wnt signaling pathway inhibitor 1)
Diseases named in the same sentence as DKK1 in open-access papers (continued):
Sharing a sentence is not in itself a finding about the gene and the disease.
tumor (continued). "Several preclinical studies on both in vitro cellular and in vivo animal models have demonstrated that DKK1 overexpression could accelerate tumor development, invasion, and metastatic spread; these inferences are in line with the findings of this investigation." (PMID 38376441, 2024). "To further investigate whether CAFs at the tumor site suppress NK cell functions by producing DKK1, we co-cultured tdT+ CAFs isolated from orthotopic tumors in aSMA-Dkk1WT-tdT mice, together with NK cells and CTV-labeled PyMT tumor cells in the presence of IgG or mDKN01." (PMID 38659818, 2024). "However, in these clinical trials, the effectiveness of the treatment may depend on the amount of DKK1 that is expressed by the patient’s own tumor." (PMID 37173977, 2023). "Therefore, in this study, we investigated whether the inhibition of DKK1 using WAY-262611 (WAY), a small molecule DKK1 inhibitor, enhances the anti-tumor efficacy of SOR in HCC." (PMID 38012711, 2023). "This variability could stem from differences in the functions of AURKA and its downstream targets in various tumor types, akin to other genes such as DKK1 and Fam20C, which exhibit varying prognostic implications in different cancer types within pan-cancer studies." (PMID 37965456, 2023). "DKK1 inhibitors combined with PD-1 monoclonal antibodies could achieve better tumor control." (PMID 37016422, 2023). "Therefore, the inactivation of Wnt/β‐catenin signalling by NSC‐CM could be attributed to NSC‐released DKK1 in the tumour microenvironment." (PMID 37410396, 2023). "Using a co-culture model of CRC organoids and T cells, researchers screened a series of small molecule inhibitors and found that DKK1 inhibitors could significantly enhance the killing effect of T cells and promote apoptosis of tumor cells by regulating the GSK3ß-E2F1-T-bet axis in CD8+ T cells." (PMID 37016422, 2023). "In addition, low levels of DKK1 expression associated with larger tumours, higher tumour grade, and ER and PgR negative tumours." (PMID 38036593, 2023). "DKK1 could act as a tumor suppressor or driver, depending on the tumor origin." (PMID 37835450, 2023). "In addition, DKK1 also played a significant role in the tumor microenvironment (TME)." (PMID 37835450, 2023). "Given the role of Dkk-1 in tumour propagation and bone destruction in malignant bone diseases, we hypothesised that blockade of Dkk-1 could have a dual role in the inhibition of bone destruction and tumour expansion." (PMID 35277659, 2022). "The downregulation of DKK1 may allow tumor cells to escape NK-cell-mediated cytotoxicity." (PMID 35693786, 2022). "Furthermore, the IPA data highlighted upregulation of sequences associated with the death of immune, lymphatic, connective tissue upon treatment with DkkMo, suggesting that Dkk-1 blockade might contribute to the depletion of the tumour stroma." (PMID 35277659, 2022). "However, the role of DKK1 as a tumor suppressor or oncogene varies across various malignant tumors." (PMID 35121803, 2022). "DKK1 may reduce tumor cell migration and invasion by inhibiting the expression of β-catenin." (PMID 35693786, 2022). "Therefore, targeting Dkk-1 in OS tumours could reduce the expansion and survival of tumour cells, increase susceptibility to chemotherapeutics, and restore the capacity of bone to repair itself." (PMID 35277659, 2022). "Overexpression of DKK1 could modulate the anti-tumor immune populations within the tumor mice." (PMID 34093545, 2021). "Importantly, we found that PRKDC could inhibit the tumor-suppressive function of ZBTB38, as PRKDC knockdown resulted in the increase of DKK1 expression and enhanced the tumor-suppressive function of ZBTB38." (PMID 34697293, 2021). "In addition, SP600125 could be an alternative adjuvant therapy for decreasing tumor size in dogs and humans with spontaneous PCa that expresses high levels of Dkk-1." (PMID 34437475, 2021). "Moreover, DKK1 expression in tumours with PXN‐AS1 silence was markedly increased." (PMID 32329150, 2020).
tumor (continued). "The bioinformatic contrasts focused on three differential gene expression analyses: contrast A, tumor versus control; contrast B, comparison between tumors with high and low expression of DKK1; and contrast C, comparison between tumor samples with high expression of DKK1 and controls." (PMID 32224864, 2020). "Thus, DKK1 acts as a tumor suppressor in PLC/PRF/5 and as a proto-oncogene in HepG2/C3A." (PMID 31568519, 2019). "The fact that DKK-1 expression in PC tissue is heterogeneous limits the diagnostic value of DKK-1 and may explain the lack of correlation between tumor and serum DKK-1 concentrations." (PMID 30116403, 2018). "In this perspective, Dkk1 could be acknowledged as a tumor suppressor protein." (PMID 29776381, 2018). "Therefore, we hypothesized that in OS, miR-107 serves as a tumor suppressor and negatively targets Dkk-1, which in turn influences the Wnt/β-catenin signal pathway." (PMID 28682874, 2017). "Furthermore, inhibition of DKK1 by neutralization decreased tumor growth." (PMID 28178355, 2017). "Finally, Pr(DKK1 - Off |Sample - Tumor, Me - M) being high is the fraction of number of 0’s in thetumorous sample (d×p) and the sum of total number of tumoroussamples and number of 0’s in the normal samples, i.e the methylated geneexpression values in normal samples (D)." (PMID 27547217, 2016). "Similarly, Pr(DKK1 - On |Sample - Tumor, Me - UM) being low is the fraction of number of 1’s in thetumorous sample (b×p) and the sum of total number of tumoroussamples and number of 1’s in the normal samples, i.e., the non-methylated geneexpression values in normal samples (B)." (PMID 27547217, 2016). "However, in the families carrying LRP5 gain‐of‐function mutations, increased incidence of cancer is not reported, and tumor developments in Sost‐ or Dkk1‐deficient animals are not observed." (PMID 26941261, 2016). "Similarly, Pr(DKK1 - On |Sample - Tumor, Me - UM) being low is the fraction of number of 1’s in thetumorous sample (b×(1−p)) and the sum of total number oftumorous samples and number of 1’s in the normal samples, i.e., thenon-methylated gene expression values in normal samples (B)." (PMID 27547217, 2016). "Moreover, DKK1 significantly promotes NSCLC tumour cells to migrate, invade and proliferate." (PMID 27240974, 2016). "Finally, Pr(DKK1 - Off |Sample - Tumor, Me - M) being high is the fraction of number of 0’s in thetumorous sample (d×(1−p)) and the sum of total number oftumorous samples and number of 0’s in the normal samples, i.e., the methylatedgene expression values in normal samples (D)." (PMID 27547217, 2016). "Our findings may help to clarify the role of DKK-1 as a tumor suppressor or metastasis promoter." (PMID 25788273, 2015). "However, DKK1 inhibits tumor growth by decreasing tumor angiogenesis and vascular perfusion." (PMID 24091497, 2014). "However, there is increasing data from preclinical studies suggesting that DKK-1 may have direct effects on tumour proliferation and cell cycle." (PMID 25182503, 2014). "However, DKK-1 expression within the tumour was very heterogeneous." (PMID 25182503, 2014). "In addition, there is increasing data to suggest direct tumor promoting effects of DKK-1." (PMID 25182503, 2014). "However, it remains unclear to what extent DKK-1 serum levels are tumour derived, or if high levels of circulating DKK-1 from other sites promote tumour growth and/or resistance to therapy." (PMID 25182503, 2014). "The data suggest that linc00467 may play a role in tumourigenesis through reducing DKK1 expression, leading to enhanced tumour cell viability, and that N-Myc-mediated suppression of linc00467 gene transcription counterintuitively blocks N-Myc-mediated cell survival." (PMID 24586304, 2014).
tumor (continued). "Moreover, overexpression of DKK1 not only enhances the tumor formation efficiency and tumor growth but also promotes the cell invasion and metastasis in vitro and in vivo, whereas knockdown of DKK1 significantly reduced both migratory and invasive abilities of HCC cells." (PMID 24325363, 2013). "Restoration of DKK1 expression by a demethylating agent 5-azacytidine in T98 GBM cells enhances their susceptibility to camptothecin- and etoposide-induced apoptosis, suggesting that treatment of GBM cells with inhibitors of promoter methylation for tumor suppressors facilitates drug efficacy." (PMID 23516171, 2013). "Moreover, blocking DKK-1 also resulted in reduction of tumor growth." (PMID 23818912, 2013). "Therefore, whether DKK1 is an oncogene or a tumor suppressor in HCC remains to be further investigated." (PMID 24325363, 2013). "However, the role of DKK1 in tumor biology is controversial." (PMID 24325363, 2013). "Furthermore, HER-2/neu overexpression was observed in only one DKK1-positive tumour." (PMID 17245340, 2007). "In addition, a humoral response may be involved, as antigen-presenting cells can take up secreted tumour-derived DKK1 and elicit a CD4+ helper T-lymphocyte response." (PMID 17245340, 2007). "Interestingly, DKK1 could have potential applications as a secreted tumour marker for cancer diagnosis, staging and monitoring of relapse." (PMID 17245340, 2007). "It is unclear at this point whether the elevated systemic Dkk-1 in OS patients is derived solely from the tumour, since the human Dkk-1 circulating in the blood of recipient mice was much lower than the mean levels detected in the blood of the human OS patients." (PMID 17987039, 2007). "Its interaction with DKK1 and subsequent activation of the PI3K/AKT pathway underscores its role in promoting tumor growth." (PMID 41149482, 2025). "This study aimed to evaluate the gene expression profiles of DKK1, HOXC6, and YKT6 in OSCC patients and explore their potential roles in tumour progression." (PMID 41477365, 2025). "Because DKK1 is also expressed by cancer epithelial cells in TNBC patient samples, next we assessed the relative importance of CAF-derived DKK1 versus tumor cell-derived DKK1." (PMID 39885132, 2025). "Our panel of VHH leads that bind to DKK1 CRD1 also show tumor suppression, whereas CKAP4 binding to DKK1 CRD1 leads to tumor progression." (PMID 40394415, 2025). "In their study, it was determined that DKK1 supports cell proliferation by binding to CKAP4, and blocking this axis inhibited tumor growth." (PMID 40922300, 2025). "To determine if DKK1 modulates the immune landscape of the TME, we profiled PyMT tumor-infiltrating immune populations from IgG or mDKN01-treated mice." (PMID 39885132, 2025). "Next, the expression of DKK1 in NB tissues was elucidated by using TNM plot database analysis, and the results showed that DKK1 expression in NB tissues (tumor) was higher than normal tissues (P < 0.001)." (PMID 40804038, 2025). "However, the oncogenic and tumor suppressive effects of DKK1 on cancer cells remain unclear." (PMID 40922300, 2025). "It has been shown that binding of DKK1 to CKAP4 leads to cell proliferation, while anti-CKAP4 antibodies seem to have anti-tumor activity." (PMID 39795613, 2025). "Elevated serum DKK-1, a Wnt signaling modulator, serves as a prognostic biomarker in HCC by driving tumor stemness, angiogenesis, and invasion." (PMID 40606973, 2025). "Knockdown of DKK1 or CKAP4 inhibited cell proliferation, and the anti-CKAP4 antibody seems to suppress tumor formation." (PMID 39795613, 2025). "Next, to further understand the local effects of DKK1 in the TME, we isolated tdT+ CAFs from primary tumors in αSMA-Dkk1cKO-tdT and αSMA-Dkk1WT-tdT mice and co-injected them with PyMT tumor cells (1:1 ratio) into the MFP of naïve WT recipient mice." (PMID 39885132, 2025).
tumor (continued). "The interaction between DKK1 and CKAP4 is essential for the proliferation of HCC cells, suggesting that the binding of these molecules is a critical step in tumor progression." (PMID 41149482, 2025). "The antibodies that target DKK1 CRD1 are involved in the immune response activation and inhibit tumor growth in all four tumor lines, indicating its potential universal role in cancer therapy." (PMID 40394415, 2025). "This pathway constituted 19 upregulated and 15 downregulated genes, amongst which were DKK1 and DKK4, which were the two most upregulated genes in the G3 tumor." (PMID 39245631, 2025). "Through the CLRN1-AS1/miR-217/DKK1 axis, the ectopic expression of CLRN1-AS1 suppresses the cell proliferation and clonogenicity, increases caspase-3 activity, decreases tumor growth in vivo, and inhibits the Wnt/β-catenin signaling pathway." (PMID 39702128, 2024). "The embryonal HBTOs were enriched with WNT target genes and EMT markers, including AXIN2, LEF1, DKK1, NOTUM, NKD1 and VIM, in line with the embryonal tumor signature." (PMID 39567475, 2024). "Dkk1-IRS was quantified based on its cytoplasmic staining and used to determine its expression level in tumour cells." (PMID 38254908, 2024). "This study identifies that DKK1-SE drives DKK1 expression by recruiting AP1 transcription factors, exerting oncogenic effects in PDAC, and enhancing the complexity of the tumor microenvironment." (PMID 39107271, 2024). "Nevertheless, it is still unclear how DKK1 expression, HNSCC prognosis, and tumor-infiltrating lymphocytes are related." (PMID 38376441, 2024). "DKK1 is a 35-kDa protein belonging to the DKK gene family, and is known for its involvement in the regulation of tumor proliferation, invasion, and metastasis, as well as the extracellular microenvironment." (PMID 38376441, 2024). "Regarding ceRNA networks, CLRN1 antisense RNA 1 (CLRN1-AS1)/miR-217/ Dickkopf-related protein 1 (DKK1) and H19/miR-93a/autophagy related 7 (ATG7) are the identified tumor suppressive ceRNA that suppresses miR-217 and miR-93a, respectively." (PMID 39702128, 2024). "This study demonstrated the characterization of intra-tumor infiltration patterns in HCC and identified DKK1+ tumor cells impeding the infiltration of CCL19+ fibroblasts and plasma cells into the tumor area that induced immunosuppressive TME." (PMID 39505867, 2024). "DKK1 is an inhibitor of the WNT signaling pathway, which is upregulated in some cancer types and is involved in tumor proliferation, invasion, and immunosuppression." (PMID 37017469, 2023). "It is also shown that MSCs can release anti-tumor factors, including IGFBP, Dkk-1, miR-16, TRAIL, IFNα, and oncostatin-M." (PMID 37681882, 2023). "The expression of DKK1 and CKAP4 is essential for tumor formation in vivo, suggesting that CKAP4 is a potential molecular target for HCC therapy." (PMID 37835450, 2023). "Since Dkk1 could be one of potential therapeutic targets further studies are needed to determine, whether there is a difference between expression of Dkk1 in tumour tissue and serum of the patient and how any of those would influence the potential use of therapeutics for EC." (PMID 36969079, 2023). "Among them, DKK1 is a member of the DKK family and regulates cell proliferation, migration, and apoptosis in various tumor tissues through β-catenin-dependent and β-catenin-independent mechanisms." (PMID 39282247, 2023). "When DKK1 was overexpressed in our Nicd/Akt model, we found a significant increase in FOXP3+ cells within tumour boundaries (p = .0076)." (PMID 35924447, 2023). "Our findings showed that CTTN enhances tumor initiation and increases anti-HER2 drug resistance by activating the DKK-1/Wnt/β-catenin signaling pathway." (PMID 36831511, 2023). "Dickkopf-1 (DKK1) is a member of the DKK Family and a secretory glycoprotein, that is tumour-specific and highly expressed in adult liver and other gastrointestinal neoplasms." (PMID 36901717, 2023).
tumor (continued). "To investigate the role of high DKK1 expression on tumour progression, we modified a hydrodynamic tail vein injection model (HTVI) to overexpress DKK1 in tumour cells." (PMID 35924447, 2023). "Finally, we wanted to define whether mDKN‐01 shows efficacy in a more pathologically relevant, damage‐induced model of iCCA where tumours develop on the background of chronically inflamed liver with endogenous levels of DKK1, thereby better reflecting human disease aetiology." (PMID 35924447, 2023). "ln-AROD is upregulated in different tumor tissues and cells (23, –, 25), and spliced and polyadenylated lncRNA positively regulates DKK1 transcription and recruits EBP1 to the DKK1 promoter." (PMID 37036350, 2023). "DKK1 vaccination elicited strong DKK1- and tumor-specific CD4+ and CD8+ immune responses, providing extra evidence for targeting DKK1 in MM patients." (PMID 36077618, 2022). "Dkk-1 has the capacity to prevent the bone repair in OLs and MOSJ-Dkk-1 cells generate aggressive and highly osteolytic tumours in mice." (PMID 35277659, 2022). "There was a linear increase in DKK-1 levels with increasing BCLC stages, reflecting tumor progression." (PMID 36230730, 2022). "These activated stellate cells are responsible for TN-C secretion into the stroma, in which TN-C can activate oncogenic signaling cascades (Wnt/β-catenin via inhibition of DKK1 and YAP/TAZ signaling) leading to tumor progression." (PMID 35785162, 2022). "The ability of CS-E to function as a tumor promoter likely depends on the expression level of CS-E partner proteins such as N-cadherin, ROR1, and DKK1." (PMID 35712490, 2022). "We further investigated the effects of DKK-1 on cancer cell proliferation, invasion, and angiogenesis in vitro and of anti-DKK-1 antibody treatment on tumor growth in vivo." (PMID 35269944, 2022). "Additional connections suggest the inhibition of Wnt signaling (DKK1–KREMEN) and mechanisms with tumor suppression capacity (DCC–NTN1)." (PMID 35053442, 2022). "MM cells try to combat this effect by releasing secreted frizzled-related protein 2 (sFRP2), Dickkopf-related protein 1 (DKK1), and trans-forming growth factor beta (TGF-β) to conquer the tumor-suppressive outcomes of osteoblasts." (PMID 36547163, 2022). "The primary tumor secretes different factors—such as CCL2, IL6, lysyl oxidase (LOX) and DKK1—into the circulation to create a pre-metastatic niche in the bone by altering the bone microenvironment." (PMID 36497192, 2022). "The study highlights plasma cell burden markers DKK1 and BCMA and validates DW-MRI MY-RADS RAC as biomarkers that can potentially track tumour burden at baseline and longitudinally." (PMID 36612090, 2022). "Neutralizing Dkk-1 and knocking down FGF-13 in tumor cells were able to reduce the extravasation rate." (PMID 36439519, 2022). "Although its mechanism of action on osteoblasts and MM cells remains uncertain, this oligopeptide sequesters DKK1 from LRP5/6 and reduces tumor cell growth, providing an option for managing tumor burden in MM." (PMID 35355709, 2022). "Mechanistic analyses revealed that BCSC-secreted DKK1 promotes SLC7A11 expression, decreased lipid peroxidation and increased glutathione, leading to diminished tumor ferroptosis and enhanced cancer cell proliferation in lung metastases." (PMID 35296660, 2022). "Subcutaneous injections were performed with Ace-1-Dkk-1YFP-Luc or Ace-1-VectorYFP-Luc cells in athymic mice to measure the effects of Dkk-1 and SP600125 on tumor growth." (PMID 34437475, 2021). "Expression of the DKK1 and DKK3 gene is controlled, among other mechanisms, by DNA methylation, a common epigenetic silencing tool, which is increased in many tumors and tumor cell lines." (PMID 34064046, 2021). "In this signature, up-regulated DKK1 and GRP together with down-regulated FAS and CD1B had significant correlation with tumor stage, metastasis and lymphatic invasion." (PMID 33996273, 2021).